INS (insulin)
Diseases named in the same sentence as INS in open-access papers (continued):
Sharing a sentence is not in itself a finding about the gene and the disease.
colitis (24 papers, 2014 to 2025). Inflammation of the colon. "The K8–/– mouse develops not only a colitis-like phenotype, but also changes, e.g., in glucose metabolism, insulin secretion and liver fragility, thereby obscuring what causes the colon phenotype." (PMID 34951664, 2021). "Second, it was detected that rectal insulin instillation in colitis-active phase significantly exacerbated colitis, suggesting that rectal insulin instillation should be forbidden during acute-colitis phase of IBD, which complements the deficiencies of previous studies." (PMID 38243324, 2024). "EZH2 intervention could alleviate the exacerbation of colitis caused by rectal insulin installations, as evidenced by less weight loss, less DAI score, fewer inflammatory cytokines, and a longer colon length." (PMID 38243324, 2024). "Furthermore, insulin-treated mice showed decreased colitis susceptibility accompanied by less body weight loss and clinical signs of colitis than insulin-untreated controls." (PMID 37491256, 2023). "Thus, we explored the molecular mechanism by which insulin ameliorates colitis through modulation of the gut microbiota and associated metabolites." (PMID 37491256, 2023). "Reportedly, the administration of rosiglitazone, a PPAR-γ agonist commonly used as an insulin-sensitizer in the management and treatment of T2D, to rodents exerted protective effects in chronic experimental colitis." (PMID 38315242, 2024). "Activation of mucosal insulin pathway by rectal insulin instillation exacerbated colitis by disrupting IELs subgroups and up-regulating TNF-ɑ and IL-17 expression." (PMID 38243324, 2024). "We confirmed the ability of LCA to mitigate the effects of colitis, and insulin alleviated colitis in part through LCA." (PMID 37491256, 2023). "Overall, our study demonstrates that insulin alleviates the development of colitis in murine IBD models and that this effect is mediated by altering the gut microbiota." (PMID 37491256, 2023). "In our study, we investigated the mitigating effects of insulin on inflammation in both acute and chronic murine colitis models and the expression of key cytokines involved in macrophage recruitment." (PMID 37491256, 2023). "Further analyses identified 23 upregulated and 27 downregulated metabolites in insulin-treated DSS-induced mice compared with PBS-treated mice with DSS-induced colitis." (PMID 37491256, 2023). "Insulin reproducibly reduced colitis, as shown by analysis of the colon length, histological assessments and evaluation of the goblet cells." (PMID 37491256, 2023). "We first examined the ability of insulin to alleviate acute colitis in the 2,4,6-trinitrobenzenesulfonic acid solution (TNBS)-induced acute colitis model." (PMID 37491256, 2023). "LCA treatment decreased the number of F4/80+ and iNOS+ cells in the colons of insulin-treated mice with DSS-induced colitis." (PMID 37491256, 2023). "These experiments highlight the contribution of the LCA-TGR5 axis to insulin-mediated protection against DSS-induced colitis." (PMID 37491256, 2023). "Consistently, insulin intervention significantly alleviated DSS-induced colitis, as evidenced by markedly reduced DAI scores, which were calculated by measuring body weight loss, stool consistency, and blood in the stool, and relieved colonic shortening." (PMID 37491256, 2023). "Collectively, these data suggest that insulin treatment impairs M1 macrophage polarization in colon tissues during colitis." (PMID 37491256, 2023). "Using partial least squares discriminant analysis, we observed distinct clustering of metabolites between PBS- and insulin-treated mice with DSS-induced colitis." (PMID 37491256, 2023). "Chronic PAHSA treatment in mice fed a high-fat diet improved glucose uptake and insulin sensitivity in heart, skeletal muscle, and liver and protects against colitis in the gut." (PMID 35192550, 2022).
colitis (continued). "Treg-secreted IL-10 was previously shown to protect mice from spontaneous colitis, and we were concerned that the reduced weight and increased insulin sensitivity in the IL-10fl/fl Foxp3-Cre+ mice were due to colitis." (PMID 33351782, 2021). "AAA catabolites may offer protective roles against colitis and autoimmunity and enhance insulin sensitivity because of lower systemic inflammation." (PMID 39551356, 2025). "However, Yassin reported that rectal insulin instillation alleviates colitis and colorectal carcinogenesis." (PMID 38243324, 2024). "Second, rectal insulin instillation led to disrupted phenotype and increased inflammatory cytokines in IELs, which could exacerbate colitis." (PMID 38243324, 2024). "Our study found that rectal insulin instillation exacerbated colitis through the regulatory effect of EZH2 on TRM, suggesting that both insulin inhibitor and EZH2 inhibitor could be potential drugs for IBD treatment." (PMID 38243324, 2024). "To gain a more comprehensive understanding of metabolites that may be involved in the ameliorative effect of insulin on colitis, we performed untargeted metabolomic profiling using UPLC–MS analysis." (PMID 37491256, 2023). "To further confirm the findings from the DSS-induced acute colitis model, we also conducted experiments assessing whether insulin reduces intestinal inflammation in other acute and chronic colitis models." (PMID 37491256, 2023). "Moreover, studies have shown that insulin alleviates inflammation in a murine colitis model by being instilled rectally." (PMID 37491256, 2023). "We tested our hypothesis that the effects of insulin on murine colitis models involved alterations in the gut microbiota." (PMID 37491256, 2023). "Furthermore, we transplanted fecal contents from PBS- and insulin-treated mice with DSS-induced colitis." (PMID 37491256, 2023). "Gene ontology analysis showed the top biological processes in IECs of acute colitis model, such as apoptotic process, positive regulation of insulin secretion involved in cellular response to glucose stimulus, response to hypoxia, establishment of cell polarity, and so on." (PMID 37158534, 2023). "Hence, insulin was shown to alleviate colitis by inhibiting M1 macrophage polarization in the colon." (PMID 37491256, 2023). "Given the significant differences in gut microbial communities after insulin treatment, we wanted to determine whether the effects of insulin on colitis could be attributed to the gut microbiota." (PMID 37491256, 2023). "Next, we tested the effect of insulin in the chronic DSS-induced colitis model." (PMID 37491256, 2023). "Our hypothesis in the present study was that insulin regulates colitis by modifying the gut microbiota." (PMID 37491256, 2023). "Next, we characterized the effect of insulin on DSS-induced colitis." (PMID 37491256, 2023). "In support of our hypothesis, we showed that mice receiving the microbiota of insulin-treated donors had significantly alleviated colitis compared to those transplanted with the microbiota of PBS-treated control donors." (PMID 37491256, 2023). "Insulin-treated mice showed alleviated colitis development, leading us to consider whether short-term treatment with insulin affects the gut physiology of normal mice." (PMID 37491256, 2023). "Thus, LCA is significantly associated with the compositional changes in the microbiota in insulin-treated colitis mice." (PMID 37491256, 2023). "Following these results showing abnormalities in adipose tissue, it was necessary to assess whether the insulin action in FMT-colitis group mice was normal." (PMID 36735734, 2023). "In conclusion, insulin could be a therapeutic agent with the potential to be developed into a functional anti-inflammatory agent to ameliorate colitis (as shown in the Graphical Abstract)." (PMID 37491256, 2023). "FMRP-fed mice showed improved insulin secretion and symptoms of colitis." (PMID 33800583, 2021).
colitis (continued). "In addition, studies of dextran sulfate-induced colitis mice have also shown that fecal insulin autoantibodies (IAA) levels are low." (PMID 35071141, 2021). "Moreover, we found that insulin treatment significantly reduced colitis." (PMID 37491256, 2023). "In addition to the fecal microbiota, other factors may also participate in the ameliorative effect of insulin on colitis." (PMID 37491256, 2023). "Therefore, we concluded that insulin alleviated colitis by mediating LCA production." (PMID 37491256, 2023). "We hypothesized that the effect of insulin in colitis involved alterations in the gut microbiota." (PMID 37491256, 2023). "Taken together, the transplantation of the colitis-associated dysbiotic microbiota was causally associated with impairment of FGF21-adiponectin axis, leading to metabolic abnormalities, including adipose tissue dysfunctions, dysregulated hepatic lipid metabolism, and reduced insulin sensitivity." (PMID 36735734, 2023). "Here we report the case of a gentleman with newly diagnosed T1D whose glycaemic control and insulin requirement improved whilst on a five year infusion programme of infliximab, a monoclonal antibody against TNF-alpha, for colitis." (PMID 39252097, 2024). "However, the level of fasting blood glucose was not different between the two groups, indicating that the transplantation with fecal microbiota from colitis mice caused an impairment of insulin action, but it was mild enough that it did not significantly raise blood glucose levels." (PMID 36735734, 2023). "Thus, we hypothesized that insulin alleviates colitis in the DSS model through the LCA-TGR5 axis." (PMID 37491256, 2023). "The LCA level is significantly increased in the gut contents of insulin-treated mice with DSS-induced colitis compared to those of PBS-treated mice with DSS-induced colitis, which has also been demonstrated to alleviate colitis." (PMID 37491256, 2023). "To further explore the mechanism by which insulin alleviates colitis, we used insulin to treat murine colitis models, including DSS- and TNBS-induced colitis models." (PMID 37491256, 2023). "The ameliorative effect of LCA was further examined in TGR5 knockdown mice, and the results revealed that insulin and LCA ameliorated colitis development through TGR5." (PMID 37491256, 2023). "Furthermore, rectal Insulin instillation promotes EZH2 expression and the EZH2 inhibitor GSK126 alleviates colitis." (PMID 38243324, 2024). "In conclusion, rectal insulin instillation increased the proportion of pro-inflammatory IEL subpopulations as well as inflammatory factor secretion, and decreased the proportion of the anti-inflammatory IELs, leading to the exacerbation of colitis." (PMID 38243324, 2024). "Defects in epithelial cell proliferation also play key roles in colitis pathogenesis and regeneration, but we did not observe effects of insulin on the proliferation of intestinal epithelial cells by Ki67 staining." (PMID 37491256, 2023). "This experimental approach allowed for direct examination of the effects of the cecal content, presumably bacteria, in the absence of genetic differences between PBS- and insulin-treated mice with DSS-induced colitis." (PMID 37491256, 2023). "To investigate whether depletion of LCA in insulin-treated mice impacts colitis, we treated mice with DSS-induced colitis with GW4064, a farnesoid X receptor (FXR) agonist, via oral gavage to suppress hepatic bile acid synthesis." (PMID 37491256, 2023). "Furthermore, knocking down TGR5 expression abrogated the effects of insulin and LCA on macrophages during colitis, as shown by the increased numbers of F4/80+ and iNOS+ cells in the colon." (PMID 37491256, 2023). "We concluded that the improved glucose tolerance and insulin sensitivity we observed in the SFD-fed Blimp-1fl/fl Foxp3-Cre+ mice was not due to colitis." (PMID 33351782, 2021). "However, the role and mechanism of intestinal mucosal insulin pathway in colitis and IBD have not been elucidated." (PMID 38243324, 2024).
colitis (continued). "In conclusion, activation of the insulin pathway upregulates EZH2 expression in intestinal mucosal T cells during inflammation, which in turn promoted TRM differentiation and disrupted subgroups of IELs and inflammatory cytokines, ultimately exacerbated colitis." (PMID 38243324, 2024). "Injury to epithelial cells is a colitis-initiating event that can increase epithelial barrier permeability; therefore, we examined the expression levels of Zo-1 and occludin, which were not affected by insulin treatment." (PMID 37491256, 2023). "Finally, we found that insulin alleviated colonic inflammation, as exemplified by the declines in the levels of inflammatory cytokines such as GM-CSF and IL-6 in the plasma of mice with DSS-induced colitis, and GM-CSF is a factor that induces macrophage differentiation and survival." (PMID 37491256, 2023). "This relationship between FGF21, adiponectin, and insulin might explain the changes in their levels observed in FMT-colitis group mice in this study, which were declines in FGF21 and adiponectin accompanied by elevated plasma insulin level and decreased insulin signaling in adipose tissue." (PMID 36735734, 2023).
endometriosis (24 papers, 2015 to 2025). The growth of functional endometrial tissue in anatomic sites outside the uterine body. "Using MVMR, we found a significant causal effect of genetically predicted fasting insulin (FI) levels on the risk of endometriosis." (PMID 38539234, 2024). "MVMR was implemented to estimate the causal effect for fasting insulin (FI), fasting glucose (FG), and glycosylated hemoglobin A1c (HbA1c) on endometriosis." (PMID 38539234, 2024). "The chronic elevation of insulin may contribute to systemic inflammation, potentially exacerbating the inflammatory processes associated with endometriosis." (PMID 40004777, 2025). "Our study not only confirmed the higher INS level in endometriosis patients at serum level, but also found that serum Glu might be a protective factor for endometriosis and INS might be a risk factor." (PMID 37649072, 2023). "Circulating miRNAs associated with endometriosis may drive appetite reductions and improvements in insulin sensitivity." (PMID 30982470, 2019). "At the messenger RNA level, our data indicated sustained WNT and dysregulated insulin signaling to be a feature of the dStromal early/mid populations in endometriosis cases." (PMID 39198675, 2024). "A cohort study conducted in China found that women with endometriosis had higher levels of insulin and plasma glucose." (PMID 38539234, 2024). "The number of retrieved oocytes was positively correlated with INS [0.07(0.00–0.14), P = 0.048] in endometriosis group." (PMID 37649072, 2023). "We found serum Glu is related to the number of retrieved oocytes in control group, serum INS is related to the number of retrieved oocytes in endometriosis group, while serum Glu and INS before pregnancy are related to the occurrence of GDM in two groups." (PMID 37649072, 2023). "There was heterogeneity in age at natural menopause, SBP, DBP, fasting insulin, age of menarche, T2D, and endometriosis, and they all showed MR-PRESSO-corrected results if outliers were detected." (PMID 37576957, 2023). "Marianna S has confirmed that endometriosis patients had lower glucose level and higher INS level in FF." (PMID 37649072, 2023). "Endometriosis patients had higher insulin (INS) [6.90(5.10–9.50) vs 6.50(4.80–8.90) μU/mL, P = 0.005]." (PMID 37649072, 2023). "For some robust MR estimators, such as endometriosis, age at menarche, age at natural menopause, fasting insulin, T2D, and SBP, their IVW results were supported by MR-Egger or weighted median." (PMID 37576957, 2023). "These genes are involved in oxidative stress and insulin signaling, both pathways strongly modified during endometriosis development." (PMID 25679207, 2015). "KD has demonstrated rapid improvements in insulin sensitivity and reductions in circulating insulin and glucose levels, suggesting that it could be particularly effective in metabolically vulnerable subgroups of endometriosis patients." (PMID 40920291, 2025). "One study investigating the effect of 6 months of danazol treatment found the absence of a significant difference in the basal prolactin levels as well as in the response to the TRH and insulin challenge tests between the controls and patients with endometriosis, before and after danazol treatment." (PMID 39407928, 2024). "To clarify these associations, we applied a bidirectional two-sample MR to investigate the causal effects of glycemic characteristics, including T1DM, T2DM, GDM, fasting glucose (FG), fasting insulin (FI), and glycosylated hemoglobin A1c (HbA1c), on endometriosis, and vice versa." (PMID 38539234, 2024). "We further explored whether alterations in serum Glu and INS played a role in the numbers of retrieved oocytes in endometriosis by multi-factor linear regression analysis." (PMID 37649072, 2023).
endometriosis (continued). "We further explored effects of serum Glu and INS on incidence of GDM in both groups, and found serum Glu were significantly associated with incidence of GDM in both endometriosis group (aOR 12.95, 95% CI 1.69–99.42; P = 0.014) and control group (aOR 4.15, 95% CI 1.50–11.53; P = 0.006)." (PMID 37649072, 2023). "This indicates that Sunitinib may act as PPARγ agonists, modulating lipid metabolism and inflammation and improve insulin sensitivity to suppress endometriosis development." (PMID 34367125, 2021). "Higher INS level in FF of endometriosis patients might be related to lower glucose level." (PMID 37649072, 2023). "In addition to the molecules playing a role in the insulin signaling pathway, the Endometriosis Knowledgebase also consists of several other pleiotropic genes like IL17A, MUC1, etc. that have been reported to be associated with PCOS by independent research groups." (PMID 31169291, 2019). "In the stromal compartment of endometriosis cases, we observed changes in gene expression that are likely to alter the WNT and insulin signaling pathways." (PMID 39198675, 2024). "We assessed body weight (BW) increase, glucose, and insulin levels at 12 weeks after SD or HFD feeding as a baseline study and 18 weeks (6 weeks after endometriosis-like lesions (ELL) induction) as an endometriosis study." (PMID 38559689, 2024). "A prediction model for endometriosis combining the number of previous pregnancies, CA125, fasting blood glucose (Glu) and INS, had a sensitivity of 73.9%, specificity of 67.8% and area under curve (AUC) of 0.77." (PMID 37649072, 2023). "Gene expression analysis showed that endometriosis altered the expression of Cebpa, Cebpb, Ppar-γ, leptin, adiponectin, IL-6, and HSL, which are involved in driving brown adipocyte differentiation, appetite, insulin sensitivity and fat metabolism." (PMID 30982470, 2019). "The effects of BMI, WHR, and WHRadjBMI on endometriosis, PCOS, pre-eclampsia, and UF were attenuated (95% CIs of ORs all contain 1) when adjusted for leptin, fasting insulin, or insulin sensitivity as measured by the modified Stumvoll Insulin Sensitivity Index (ISI)." (PMID 35104295, 2022). "It seems that danazol treatment of endometriosis does not lower the basal prolactin level as well as the response to the TRH and insulin challenge tests." (PMID 39407928, 2024).